BAALC (BAALC binder of MAP3K1 and KLF4)
Description:
May play a synaptic role at the postsynaptic lipid rafts possibly through interaction with CAMK2A.
Tractability: PROTAC: its protein half-life has been measured.
Gene: Protein-coding gene on chromosome 8 (103,140,433 to 103,230,305, forward strand). Ensembl gene ENSG00000164929.
Subcellular location: Cytoplasm; Synapse, synaptosome; Membrane raft; Postsynaptic density
Subcellular location (Human Protein Atlas): Cytosol; Nucleoplasm
Gene Ontology:
Cellular component: cytoplasm; cytosol; membrane raft; postsynaptic density; synapse
Genetic constraint (gnomAD): Loss-of-function variants: 8 observed, 9.97 expected, observed/expected ratio (o/e) 0.8, 90% interval 0.47 to 1.44. That is too few expected variants to judge how well the gene tolerates losing a copy. Missense variants: 169 observed, 144.38 expected, observed/expected ratio (o/e) 1.17, 90% interval 1.03 to 1.33. Synonymous variants: 77 observed, 58.63 expected, observed/expected ratio (o/e) 1.31, 90% interval 1.09 to 1.59.
Homologues: Orthologues: chimpanzee BAALC (98% identical), macaque BAALC (96% identical), pig BAALC (85% identical), mouse Baalc (83% identical), guinea pig BAALC (59% identical), rat Baalc (58% identical), tropical clawed frog baalc (52% identical), zebrafish baalcb (40% identical), zebrafish baalca (31% identical).
Diseases named in the same sentence as BAALC in open-access papers:
BAALC is named in the same sentence as 30 diseases in open-access papers, as found by Europe PMC text mining. Sharing a sentence is not in itself a finding about the gene and the disease. The quoted sentences say what the papers report.
acute myeloid leukemia (14 papers, 2012 to 2025). Acute myeloid leukemia (AML) is a group of neoplasms arising from precursor cells committed to the myeloid cell-line differentiation. "BAALC expression has also been associated with acute lymphoblastic leukemia and acute myeloid leukemia." (PMID 40242470, 2025). "High BAALC expression levels at acute myeloid leukemia diagnosis have been linked to adverse outcomes." (PMID 29152132, 2017). "Eight genes (BAALC, CD14, CD34, CD74, DNTT, HLA-DRA, IRF8, and MN1) were all associated with “leukemia” (P = 1.15 × 10−4), “acute myeloid leukemia” (P = 9.37 × 10−3), and “proliferation of myeloid cells” (P = 0.044)." (PMID 26517675, 2015). "The aim of this work was to evaluate the prognostic value of BAALC gene expression in Egyptian children with acute myeloid leukemia." (PMID 25960861, 2015). "BAALC is an overexpressed gene usually found in a subset of patients with acute myeloid leukemia within neuroectoderm-derived and mesoderm tissues." (PMID 24780490, 2014). "BAALC seems to be relevant, not only for differentiating acute myeloid leukemia but also for prognosis in adult T-ALL; high BAALC and ERG expressions are associated with a high risk of relapse and inferior survival." (PMID 22348024, 2012). "In the future, prospective studies should evaluate whether acute myeloid leukemia patients with high pre-HSCT BAALC/ABL1 copy numbers benefit from additional treatment before or early intervention after HSCT." (PMID 29152132, 2017). "Recent data indicate that high BAALC expression levels may also be used as marker for residual disease following acute myeloid leukemia treatment." (PMID 29152132, 2017). "In addition to these in vitro findings, in young patients with acute myeloid leukemia, higher BAALC gene expression correlates inversely with miR-148a expression, and has been shown to associate with worse outcome in patients treated with chemotherapy." (PMID 23056401, 2012). "In terms of the p-value (padj), the most deregulated gene is BAALC (Brain And Acute Leukemia, Cytoplasmic), a gene responsible for acute myeloid leukemia (AML), and known to potentiate the oncogenic ERK pathway through interaction with MEKK1 and KLF4." (PMID 40700096, 2025). "Establishing a stepwise model of congenital neutropenia to acute myeloid leukemia (AML), derived from congenital neutropenia patient-derived iPSCs by CRISPR/Cas9, revealed that BAALC and MK2a phosphorylation may be excellent targets for preventing leukemogenic transformation or eliminate AML blasts." (PMID 34887928, 2021). "Currently, the function of BAALC is not fully characterized, but studies indicate a high clinical significance in pathological processes from several leukemias [Acute Lymphoblastic Leukemia and Acute Myeloid Leukemia to trisomy 8/Warkany syndrome 2]." (PMID 32240523, 2020).
acute leukemia (10 papers, 2010 to 2025). A clonal (malignant) hematopoietic disorder with an acute onset, affecting the bone marrow and the peripheral blood. "At diagnosis, high expression of the AML-associated genes BAALC (brain and acute leukemia, cytoplasmic) and MN1 (meningioma-1) were repeatedly linked to inferior outcomes in patients consolidated with chemotherapy while data for patients receiving HSCT remain limited." (PMID 32862286, 2020). "The AML-associated genes BAALC (brain and acute leukemia, cytoplasmatic) and MN1 (meningioma-1) have been shown to be physiologically expressed at high levels in myeloid progenitor cells and downregulated during maturation and to promote leukemogenesis through blockage of myeloid differentiation." (PMID 32862286, 2020). "BAALC binder of MAP3K1 and KLF4 (BAALC), a regulator of developing neuroectoderm tissues overexpressed in acute leukemia and GBM, and a target of SOX2 in differentiated GBM cells, was upregulated in HF2303 SDCs." (PMID 39919036, 2025). "Myeloperoxidase (MPO)/lysozyme (LYZ) and marginal zone B and B1 cell-specific protein (MZB1)/brain and acute leukemia, cytoplasmic (BAALC) were respectively activated in the granulocyte-macrophage progenitor (GMP) and multilymphoid progenitor (MLP) clusters." (PMID 40036065, 2025). "BAALC is abundantly expressed in several cancer types, including acute leukemias, glioblastoma, gastrointestinal stromal tumors and melanoma." (PMID 33968759, 2021). "Another gene, Brain and Acute Leukemia, Cytoplasmic, BAALC, is also located in this region, and is overexpressed in a variety of cancer types." (PMID 33968759, 2021). "The brain and acute leukemia cytoplasmic (BAALC; UniProt entry Q8WXS3) is a 180-residue-long human protein having six known isoforms." (PMID 32240523, 2020). "The first study to propose BAALC as a potential MRD marker analyzed 45 patients with de novo acute leukemia, but also included six patients with APL and 11 patients with lymphoid leukemia in their analysis." (PMID 29152132, 2017). "The gene brain and acute leukemia, cytoplasmic (BAALC) has been suggested as a suitable MRD marker as it is expressed at low levels in peripheral blood and bone marrow of healthy individuals, but upregulated in AML patients." (PMID 29152132, 2017). "The multivariate regression test had revealed that BAALC and ERG are independent risk factors for acute leukemia, because." (PMID 27335598, 2016). "Brain and acute leukemia, the cytoplasmic gene (BAALC) and ETS-related gene (ERG) are examples of these transcription factors." (PMID 27335598, 2016). "The expression of Wilms tumor-1 (WT1), brain and acute leukemia, cytoplasmic (BAALC) and ETS-related gene (ERG) might be considered as prognostic factors in AML patients." (PMID 33747867, 2021). "The brain and acute leukemia, cytoplasmic (BAALC), which maps on chromosome 8 at 8q22.3, was originally observed in the neuroderm and its expression was reported as a hematopoietic precursor, such as the early hematopoietic cells of a cluster of differentiation 34+." (PMID 27335598, 2016). "BAALC was found overexpressed in a subset of acute leukemias." (PMID 23390598, 2013). "Among these overlapped regions, several functional genes were found, including LIM and senescent cell antigen-like domains 1 (LIMS1), myosin light chain kinase family, member 4 (MYLK4), frizzled family receptor 6 (FZD6), and brain and acute leukemia, cytoplasmic (BAALC)." (PMID 23390598, 2013).
leukemia (6 papers, 2015 to 2021). A malignant (clonal) hematologic disorder, involving hematopoietic stem cells and characterized by the presence of primitive or atypical myeloid or lymphoid cells in the bone marrow and the blood. "As BAALC regulates leukemia cell proliferation in vitro, we firstly examined the effects of BAALC overexpression on the proliferative capacity of MCF-7 breast cancer cells." (PMID 33968759, 2021). "Brain and Acute Leukemia, Cytoplasmic (BAALC) is a protein that controls leukemia cell proliferation, differentiation, and survival and is overexpressed in several cancer types." (PMID 33968759, 2021). "As a novel regulator for APA events, FIP1L1 can regulate the 3’UTR lengthening of leukemia-associated genes, including NRAS, BAALC, and MAPKAPK3." (PMID 34195183, 2021). "As BAALC acts as a scaffolding protein in leukemia cells, we identified that BAALC binds to FAK, which may explain the pro-migratory and invasive properties of BAALC overexpression in breast cancer cells." (PMID 33968759, 2021). "Further researches still needed to clarify the role of BAALC and ERG in the pathogenesis of leukemia and their importance as targets for treatment of AML." (PMID 27335598, 2016). "Further researches still needed to clarify the role of BAALC and ERG in the pathogenesis of leukemia and their importance as targets for treatment of AML that could be promising due to their high incidence of expression in AML." (PMID 27335598, 2016). "In addition, high levels of BAALC expression were present in leukemic blasts in subsets of acute lymphoblastic leukemia (ALL) and AML patients with a normal karyotype, it may act as an adverse prognostic factor through prompting proliferation and inhibiting apoptosis in leukemia cells." (PMID 27335598, 2016).
breast carcinoma (4 papers, 2016 to 2025). "An Alu insertion in an upstream enhancer of the CBL tumor suppressor gene is associated with down-regulation of the gene in a single breast cancer patient, and an L1 insertion in the first exon of the BAALC gene also disrupts its expression in head and neck squamous cell carcinoma." (PMID 27900322, 2016). "The knockdown of BAALC expression reduced the abilities of proliferation, invasion and migration for breast cancer cells." (PMID 38816411, 2024). "We show that overexpression of BAALC in MCF-7 breast cancer cells increases the proliferation, anchorage-independent growth, invasion, and migration capacity of these cells." (PMID 33968759, 2021). "Our data demonstrate a novel function for BAALC in the control of breast cancer metastasis, offering a potential target for the generation of anti-cancer drugs to prevent breast cancer metastasis." (PMID 33968759, 2021). "BAALC protein expression was examined by immunohistochemistry in breast cancer, and matched lymph node and normal breast tissue samples." (PMID 33968759, 2021). "We demonstrate herein that BAALC is overexpressed in breast cancer, and that this overexpression predicts for shorter OS and distant metastasis free survival (DMFS) for breast cancer patients." (PMID 33968759, 2021). "In conclusion, we have identified a new mechanism for enhancing breast cancer metastasis, specifically BAALC overexpression." (PMID 33968759, 2021). "As we identified that increased BAALC mRNA expression was associated with significantly worse DMFS, we examined migration and invasion following BAALC overexpression in MCF-7 breast cancer cells." (PMID 33968759, 2021). "Taken together, these results suggest that BAALC overexpression in breast cancer cells leads to phosphorylation of FAK and secretion of MMP-9, resulting in increased capacity for migration and invasion and ultimately higher risk of metastasis." (PMID 33968759, 2021). "Functional effects of BAALC expression on breast cancer proliferation, migration and invasion were determined in vitro." (PMID 33968759, 2021). "Herein, we show that BAALC overexpression increases breast cancer cell invasion, migration and anchorage-independent growth." (PMID 33968759, 2021). "The mean expression of BAALC was significantly higher in breast cancer (p = 0.0459) and metastases (p = 0.0206) compared to normal breast tissue." (PMID 33968759, 2021). "This study investigates BAALC expression in human breast cancers with the aim of determining if it plays a role in the pathogenesis of the disease." (PMID 33968759, 2021). "We demonstrate herein that BAALC expression is progressively increased in primary and breast cancer metastases when compared to normal breast tissue." (PMID 33968759, 2021). "BAALC expression was examined in normal human breast, breast cancer, and lymph node metastasis tissue by immunohistochemistry." (PMID 33968759, 2021). "A full-length form of BAALC was transfected into MCF-7 breast cancer cells, which have low levels of endogenous BAALC expression." (PMID 33968759, 2021). "Conversely, siRNA knockdown of BAALC expression in Hs578T breast cancer cells decreases proliferation, invasion and migration." (PMID 33968759, 2021). "By contrast, decreasing BAALC expression in Hs578T cells decreased breast cancer cell migration and invasion." (PMID 33968759, 2021). "In light of this, the present study examined the expression of BAALC in breast cancer, and characterized the role of BAALC overexpression in breast cancer proliferation, invasion and migration." (PMID 33968759, 2021). "Our data presented herein show that BAALC is overexpressed in primary breast cancer and lymph node metastases compared to normal breast tissue, suggesting that it may play a role in breast cancer progression." (PMID 33968759, 2021).
breast carcinoma (continued). "We show that breast cancer cell proliferation, invasion and migration is increased with BAALC overexpression, and decreased with BAALC suppression, suggesting that BAALC may be a driver of breast cancer metastasis." (PMID 33968759, 2021). "BAALC overexpression enhances breast cancer cell proliferation, invasion and migration in vitro." (PMID 33968759, 2021). "Taken together with our data demonstrating that BAALC is overexpressed in metastases, this indicates that BAALC overexpression may enhance breast cancer metastasis." (PMID 33968759, 2021). "We therefore next examined whether BAALC overexpression could alter processes involved in the metastasis of breast cancer cells." (PMID 33968759, 2021). "Indeed, increased BAALC mRNA was associated with significantly worse PFS and DMFS in breast cancer patients, indicating that high BAALC mRNA is a potential novel biomarker for breast cancer patient outcome." (PMID 33968759, 2021). "However, the precise cellular functions controlled by BAALC in breast cancer cells remains largely unexplored." (PMID 33968759, 2021). "This study raises the possibility that BAALC may be a novel prognostic marker for breast cancer, and also a target for controlling breast cancer cell metastasis." (PMID 33968759, 2021). "Taken together, our data indicate that BAALC directly interacts with FAK, and that BAALC overexpression led to an increase in the expression of active MMP-9 suggesting that BAALC may enhance breast cancer cell migration and invasion through a FAK and MMP-9-mediated mechanism." (PMID 33968759, 2021). "Finally, reverse co-immunoprecipitation revealed a direct association between FAK and BAALC in these breast cancer cells, suggesting that BAALC overexpression may be enhancing breast cancer cell migration via a FAK-mediated pathway." (PMID 33968759, 2021). "have recently identified a role for BAALC overexpression in controlling triple negative breast cancer cell proliferation and invasion, and our results confirm this finding in an additional triple negative breast cancer cell line as well as extend this finding to luminal A breast cancer cells." (PMID 33968759, 2021). "As several pathways are known to mediate breast cancer metastasis, including FAK and ERK, and BAALC potentiates the ERK pathway in AML cells, we examined expression and phosphorylation of FAK and ERK in EV and BAALC overexpressing MCF-7 cells." (PMID 33968759, 2021). "Increased BAALC mRNA is associated with a reduction in DMFS and disease-free survival, but not OS, in breast cancer patients, even when corrected for tumor grade." (PMID 33968759, 2021). "We show herein that BAALC overexpressing cells exhibit significantly higher levels of p-Y397 FAK, and that inhibiting FAK, but not ERK, can decrease the enhanced BAALC-mediated breast cancer cell migration." (PMID 33968759, 2021). "We show herein that BAALC overexpression also increases breast cancer cell proliferation, indicating that this BAALC-mediated enhancement of proliferation is not restricted to hematopoietic cells." (PMID 33968759, 2021). "By contrast, following BAALC overexpression in MCF-7 breast cancer cells, we did not observe an increase in ERK activation, indicating that the BAALC overexpression induced increase in proliferation is not mediated via the oncogenic ERK pathway in MCF-7 cells." (PMID 33968759, 2021). "However, the expression and potential role of BAALC in breast cancer has not widely been examined." (PMID 33968759, 2021). "BAALC overexpression led to an increase in the expression of active MMP-9, but not active MMP-2, compared to EV expressing MCF-7 breast cancer cells." (PMID 33968759, 2021). "Additionally, we show that BAALC can interact with focal adhesion kinase (FAK), an established promoter of tumor progression and metastasis, indicating that this BAALC mediated enhancement of breast cancer cell migration and invasion may be controlled by a FAK-dependent mechanism." (PMID 33968759, 2021).
triple-negative breast carcinoma (4 papers, 2020 to 2022). An invasive breast carcinoma which is negative for expression of estrogen receptor (ER), progesterone receptor (PR), and human epidermal growth factor receptor 2 (HER2). "In support of this, BAALC controls cell proliferation in AML and triple negative breast cancer and when BAALC overexpression is combined with the self-renewal promoting oncogene HoxA9, leukemogenesis is induced in vivo." (PMID 33968759, 2021). "Most recent study showed that Long non-coding RNA LRRC75A-AS1 facilitates triple negative breast cancer (TNBC) cell proliferation and invasion via functioning as a ceRNA network of LRRC75A-AS1/miR-380-3p/BAALC in accelerating TNBC development, indicating new promising targets for TNBC treatment." (PMID 34557343, 2021). "BAALC is a protein whose function has not been widely studied, however it is abundantly expressed in a range of cancer types, including glioblastoma, AML, melanoma, gastrointestinal stromal tumors, and triple negative breast cancer suggesting that it may play a role in tumorigenesis." (PMID 33968759, 2021).
acute lymphoblastic leukemia (3 papers, 2015 to 2025). Leukemia with an acute onset, characterized by the presence of lymphoblasts in the bone marrow and the peripheral blood. "High BAALC gene expression was found in a subset of patients with AML, acute lymphoblastic leukemia (ALL), and blast phase of chronic myeloid leukemia (CML), whereas no BAALC expression could be detected in patients with chronic-phase CML or chronic lymphocytic leukemia (CLL)." (PMID 25960861, 2015).
glioblastoma (3 papers, 2015 to 2025). The most malignant astrocytic tumor (WHO grade IV). "Thus, our study highlights the role of BAALC in glioblastoma, making it a potential target in cancer treatment." (PMID 40700096, 2025). "Additionally, high BAALC gene expression occurs in glioblastoma, melanoma, and childhood gastrointestinal stroma tumors, suggesting an oncogenic role for BAALC gene." (PMID 25960861, 2015).